MMP9 (matrix metallopeptidase 9)
Diseases named in the same sentence as MMP9 in open-access papers (continued):
Sharing a sentence is not in itself a finding about the gene and the disease.
cancer (continued). "SERPING1, a protease inhibitor belonging to the serpin superfamily, can modulate extracellular matrix metalloproteinases (MMPs) activity, such as MMP‐2 and MMP‐9, to influence cancer cell motility." (PMID 39474998, 2025). "A similar trend was observed in circulating levels, with decreased LCN-2 and increased MMP-9 in cancer patients compared to healthy controls." (PMID 40214460, 2025). "MMP9 not only plays a role in angiogenesis, metastasis, and cancer invasion, but also contributes to the survival and spread of cancer cells." (PMID 40839565, 2025). "A notable member, MMP-9, belongs to the gelatinase subfamily and originates from inflammatory cells, tumor-adjacent stromal cells, or the cancer cells themselves." (PMID 41398969, 2025). "Previous study reported that dysadherin/MMP9 axis enhances ECM proteolytic activity and activates cancer-associated fibroblast remodeling matrix stiffness, leading to CRC progression." (PMID 40867005, 2025). "MMP9 was reported to enhance cancer metastasis to lung and liver through collagen degradation at metastatic niches." (PMID 40410902, 2025). "These NPs also inhibit the expression of MMP-2 and MMP-9, enzymes involved in cancer invasion and metastasis." (PMID 39861761, 2025). "The bioinformatics analysis of molecular docking proved significant ligand-protein interactions of CBD, THC, and humulene with cancer-associated proteins such as PD-1/PD-L1, TNF-α, and MMP-9." (PMID 40008130, 2025). "This activation increases the secretion of fibronectin and type I collagen, which in turn promotes the release of MMP-9, aiding cancer cell migration." (PMID 40230452, 2025). "Effect of CFSB, at its IC50 concentration, on the expression levels of Bax, Bcl2, caspases-3 and MMP9 in HepG2 cancer cells." (PMID 40396612, 2025). "Together, the upregulation and activation of MMP-2 and MMP-9 synergistically increase cancer cell invasiveness, enabling them to penetrate and spread throughout the body." (PMID 40322886, 2025). "Genetic variations, particularly SNPs affecting MMP-9 and IL-6, have been linked to an increased risk of VTE, especially in cancer patients." (PMID 40299499, 2025). "This was achieved by downregulating the expression of MMP-2, MMP-9, and urokinase-type plasminogen activator (u-PA), key mediators of cancer cell invasion and metastasis." (PMID 40136435, 2025). "Several studies have indicated that MMP2/MMP9 is an important prognostic factor for various cancer types." (PMID 40735254, 2025). "Increased expression of CX3CL1 recruits the CX3CR1‐positive macrophages to liver PMN, resulting in the upregulation of MMP9, which facilitated the migration of immune cells and cancer cells." (PMID 40032646, 2025). "Many clinical and experimental studies reported that the expression of MMP9 increased with cancer progression." (PMID 40839565, 2025). "Cancer progression and metastasis are significantly influenced by proteins like Matrix Metalloproteinase-9 (MMP9) and Glucose-Regulated Protein 78 (GRP78)." (PMID 40679956, 2025). "In this review, understanding how the bioactive compounds in wine influence MMPs, specifically MMP-2 and MMP-9, provides valuable insights into their potential implications for cancer therapy." (PMID 40563423, 2025). "In MCF-7 cells, AgNPs induced apoptosis through cell cycle arrest and MMP-9 suppression, consistent with silver nanoparticles’ known interactions with cancer cell pathways." (PMID 40500720, 2025). "Given that MMP-9 dysregulation plays a key role in cancer invasion, metastasis, and other inflammatory conditions, its inhibition represents a promising therapeutic strategy." (PMID 40565127, 2025). "HIF-1α enhances mitochondrial metabolism and supports cancer cell survival, while also promoting MMP-9 expression." (PMID 41303321, 2025).
cancer (continued). "Affinity‐based proteomics revealed direct binding to voltage‐dependent anion channel 1 (VDAC1), prohibitin (PHB), and matrix metalloproteinase‐9 (MMP9), which regulate cancer stemness, motility, metabolism, and apoptosis." (PMID 41179704, 2025). "NETs have been shown to play a role in this context by awakening dormant breast cancer cells through NET-derived proteases such as NE and MMP9, cleaving laminin and activating signalling pathways that resume cancer cell proliferation." (PMID 41360771, 2025). "By incorporating MMP-9-responsive peptide into the lipid nanocarrier, the nanoplatform can response to MMP-9 enzyme in cancer tissues and release therapeutic cargos." (PMID 39891180, 2025). "MMP9 facilitates extracellular matrix degradation, enabling cancer cell invasion, dissemination, and angiogenesis by attracting vascular endothelial growth factor (VEGF)." (PMID 40679956, 2025). "MMP9 levels were significantly elevated in cancer patients compared to healthy controls (p = 0.0002), regardless of histological subtype, stage, or grade." (PMID 41041068, 2025). "Increased N-cadherin expression leads to weaker adherent junctions, which in turn promote cellular motility, MMP-9 induction, and invasion in some carcinoma cell lines." (PMID 40806251, 2025). "qRT-PCR analysis displayed that the mRNA expression of MMP-2, MMP-3, MMP-7, and MMP-9 in the cervical tissue of patients with cancer was significantly greater than that in the control (p = 0.005, p < 0.001, p < 0.001, and p = 0.038, respectively)." (PMID 39247608, 2024). "It has been shown that important pathways involved in cancer progression, such as the Akt/NF-kB signalling pathway and the MMP-9 pathway, are prime targets involved in the PLB-mediated cancer response." (PMID 39275349, 2024). "The cancer-invasive activity is regulated by several MMPs, among which MMP9 can be processed by plasmin, resulting in the manifestation of active MMP9." (PMID 38595825, 2024). "Corroborating the importance of NETs in cancer cell awakening from dormancy, both disruption of NET‐DNA and inhibition of NE/MMP9 activity prevented LPS‐ and smoking‐induced cancer recurrence." (PMID 39015554, 2024). "In this study, molecular docking techniques were utilized to explore the binding interactions between silymarin and two significant matrix metalloproteinases (MMPs), MMP-2 and MMP-9, which are integral to cancer metastasis." (PMID 39431222, 2024). "These compounds target key oncogenic pathways, such as those regulated by Bcl-2, HER2, p120, MMP-2, and MMP-9—proteins essential for cancer cell survival and metastasis." (PMID 39840104, 2024). "TANs granules contain serine proteases, neutrophil elastase, MMP-9, and cathepsin G which induce cancer cells proliferation in AATs." (PMID 38969910, 2024). "Further analysis of gene expression patterns revealed a difference in the response of the KEGG Pathway in Cancer genes; again, Buparvaquone treatment had a greater effect than MC2646, notably for parasite-induced genes linked to transformation, such as mmp9." (PMID 38472173, 2024). "On the one hand, these results reveal that MMP9 is critically involved in SET-ZBTB11 complex-mediated regulation of cancer cell metastatic behaviors." (PMID 38355937, 2024). "MMP9 gene is involved in processes such as cell proliferation, migration, and invasion, which are crucial in cancer progression." (PMID 38560573, 2024). "Studies have also shown the involvement of GH in elevating MMPs, particularly MMP2 and MMP9, thereby promoting cancer cell migration and invasion." (PMID 39123364, 2024). "All of these results confirm EGCG’s ability to suppress cancer formation, mainly by modulating MMP-2, MMP-9, and associated pathways." (PMID 39335164, 2024). "Numerous genes, including MMP-2 and MMP-9, are modulated by the transcription factor NF-κB to control a range of cellular functions, for instance, adhesion, inflammation, and cancer metastasis." (PMID 38672151, 2024).
cancer (continued). "Follow-up in vivo studies using syngenic GL261 cells and human U343 cells supported that cancer cells that escaped TMZ-mediated cytotoxicity promoted the expression of MMP9." (PMID 38906916, 2024). "Elevated levels of MMP-2 and MMP-9 are often used as biomarkers for the diagnosis and prognosis of various diseases, including cancer and cardiovascular diseases." (PMID 39858430, 2024). "The accumulation of IL6 also stimulates Metalloproteinase-9 (MMP9) production in OC, promoting cancer cell invasion and degradation of the extracellular basement membrane." (PMID 39766086, 2024). "Nucleosomal DNA from NETs functions as a scaffold that allows neutrophil elastase and matrix metalloproteinase 9 (MMP9) to cleave and remodel laminin, activating integrin signalling and promoting reactivation of dormant cancer cells." (PMID 39704565, 2024). "This protein promotes cancer progression by modulating the expression of genes such as Snail and MMP9, two key proteins regulating EMT." (PMID 38612604, 2024). "MMP9 promotes metastasis of cancer cells by the degradation of the extracellular matrix and basement membrane, and the levels of MMP9 are positively related to the rate of distant metastasis." (PMID 39161904, 2024). "In conclusion, not all leaf extracts can decrease the activity of both MMP-2 and MMP-9 in cancer, which emphasizes the value of the tested chokeberry leaf extracts." (PMID 39683504, 2024). "Considerable evidence, research, and publications have indicated that MMPs, including MMP-2 and MMP-9, are actively involved in the spread of malignant cells in tumors by increasing cancer-cell growth, migration, invasion, and angiogenesis." (PMID 38893149, 2024). "Based on the overexpressed MMP‐9 of cancer cells, the process of nanoparticle assembly process occurs near the cell membrane, leading to a size‐induced selection of cellular uptake mechanisms, resulting in diminished cell growth." (PMID 39439489, 2024). "The cancer foci were significantly smaller in the resveratrol groups, possibly due to the decreased activity of MMP-9 in plasma, as confirmed using gelatin zymography." (PMID 39335164, 2024). "The study’s findings that inhibitors of ERK1/2, JNK, and p38 MAPK can partially block CA-induced MMP9 expression underscore the crucial role of these kinases in mediating MMP9’s involvement in cancer cell invasion." (PMID 39664453, 2024). "In previously study, we employed BNE-RRC to effectively inhibit cancer cell growth by regulating key proteins associated with cancer development, growth, and survival, such as COX2, AKT, GRP78, and MMP9." (PMID 39273519, 2024). "The gingipain protease Porphyromonas gingivalis activates NF-κB and MMP-9 in oral squamous cells, which are important for cancer cell invasion and metastasis." (PMID 38685022, 2024). "The activation of the PI3K/Akt signaling pathway can regulate cancer cell metastasis by increasing the expression of MMP-9 at the transcriptional level." (PMID 39062099, 2024). "MMPs, particularly MMP-2 and MMP-9, are key in governing cancer invasion and metastasis by degrading the ECM and promoting EMT." (PMID 38693104, 2024). "The inhibition of the MMP-9-BCL-2-dependent AMPK activation pathway by AgNPs leads to the suppression of mTOR activation, hindering the subsequent pathways linked to cancer proliferation." (PMID 38575697, 2024). "MMP-2 and MMP-9, two important matrix metalloproteinases, have a significant impact on the invasion and metastasis of cancer cells." (PMID 38434979, 2024). "The activation of the MAPK and NF-κB pathways enhances the expression of MMP-2 and MMP-9, thus promoting cell invasion and migration and cancer disease progression." (PMID 39335164, 2024). "We believe that this approach can open new avenues for MMP-9-based biomedical detection at the early cancer stage and provide guidance for pathophysiological mechanism studies, cancer diagnosis, and therapy." (PMID 38240894, 2024).
cancer (continued). "RA’s anticancer properties have been demonstrated in in vitro, in vivo, and in silico models, particularly through the activation of apoptotic pathways and the inhibition of key enzymes, like MMP-2 and MMP-9, which are involved in cancer metastasis." (PMID 39594455, 2024). "We further verified the metastatic ability of the cancer cells caused by the LMF exposure by assessing two metastasis-related proteins, matrix metalloproteinases MMP2 and MMP9, which both were significantly increased." (PMID 39336161, 2024). "In turn, the activation of NF-κB controls the cancer cells invasiveness, migration, and metastasis by modulating the expression of E-cadherin, N-cadherin, MMP-9, MMP-3 and β-actin." (PMID 38397187, 2024). "Clinical data have already confirmed that soluble factors MMP-14 and MMP-9 play roles in the effectiveness of regorafenib in relation to cancer progression and metastasis." (PMID 39199626, 2024). "All derivatives were initially screened using the MTT assay to evaluate cytotoxic effects on normal colonocytes for safety assessment, followed by evaluation of their anti-cancer potential on HCT 116 cells overexpressing MMP-9 and MAO-A." (PMID 39858430, 2024). "Plasma levels of MMP-2 and MMP-9 were significantly elevated in the DMH-induced cancer group compared to the control group." (PMID 39858430, 2024). "By releasing elevated levels of vascular endothelial growth factor (VEGF) and matrix metalloproteinase (MMP)-9, neutrophils enhance angiogenesis at the tumoral site, promoting cancer development and progression." (PMID 38910770, 2024). "We analyzed the expression of MMP-2 and MMP-9 on MDA-MB-231 cancer cells after treatment with DiMeOC-Mg-BCD (at CC50) for 48 h by RT-PCR." (PMID 38673967, 2024). "By unveiling the role of TGF-β and TNF-α in promoting MMP-9 expression through epigenetic modifications, we provide a foundation for future investigations into the complex molecular interactions that drive cancer metastasis." (PMID 39351229, 2024). "Curcumin downregulates MMP-2 and MMP-9, thereby impairing the invasive capabilities of cancer cells." (PMID 39061221, 2024). "By curtailing the phosphorylation of STAT3 and the subsequent expression of downstream genes like MMP-2 and MMP-9, apigenin exerts a suppressive effect on the invasion and migration of cancer cells." (PMID 38939095, 2024). "In particular, the expression and activity of MMP-2 and MMP-9, also known as gelatinases or type IV collagenases, are correlated with the aggressiveness of cancer and a poor prognosis." (PMID 39335164, 2024). "This stimulatory effect was attributed to NET-derived proteases NE and MMP9, which remodel laminin and activate signaling via integrin α3β1, subsequently promoting cancer cell proliferation." (PMID 38672433, 2024). "The matrix metalloproteinase-9 (MMP-9) protein was theorized as a potential single-protein marker, as it is known to have functional roles in cancer cell survival and metastases." (PMID 38673779, 2024). "Downregulation of p38 MAPK leads to suppressed expression and activity of matrix metalloproteinases MMP-2 and MMP-9, supporting the role of p38 in facilitating cancer cell invasion." (PMID 38806469, 2024). "This inhibitor can be utilized to assess the effectiveness of MMP-9 inhibition as a treatment option for cancer patients." (PMID 39858430, 2024). "Vanillin has been demonstrated to decrease MMP-9, an enzyme responsible for extracellular matrix disintegration, which aids cancer cell invasion and metastasis." (PMID 39451522, 2024). "Results from cell scratch assays demonstrated that the increased expression of MMP9 recovered the migration capacity of MED1 knockdown cancer cells." (PMID 39343952, 2024). "This notion was confirmed by investigating SET-ZBTB11 complex-mediated transcriptional activation of MMP9, a key matrix metallopeptidase for extracellular matrix degradation that facilitates cancer cell migration and invasion." (PMID 38355937, 2024).
cancer (continued). "Regardless, these results suggest that the anti-cancer agent TMZ promotes the expression and activity of MMP9 in vivo, and that prolonged TMZ treatment can cause adverse effects in GBM patients by stimulating metastasis through activation of MMP9." (PMID 38906916, 2024). "Regarding cancer proliferation and invasion-associated markers, Ki67, MMP2, and MMP9 protein levels were significantly decreased following PLK1 knockdown relative to the si-NC group." (PMID 39524172, 2024). "Three different proteases—Tobacco, Etch Virus (TEV), the main protease from coronavirus SARS-COV-2 (Mpro) and Matrix Metallopeptidase 9 (MMP9)—a cancer-selective human protease—were examined." (PMID 38646011, 2024). "Activation of this pathway by B7-H3, a co-stimulatory molecule known for its elevated expression in various cancers, significantly upregulates MMP9." (PMID 39664453, 2024). "The carcinogenic process is believed to involve MMP-2 and MMP-9 in order to angiogenesis and metastasis occurring in various cancer cell lines." (PMID 39497156, 2024). "HOTAIR promotes matrix metalloproteinase (MMP‐2 and MMP‐9) activity for cell motility and the capacity to dissolve the basement membrane contributing to the invasion of cancer cells." (PMID 39725668, 2024). "VEGF expression correlates positively with MMP-2 and MMP-9, and inhibiting MMP-9 levels can suppress cancer cell proliferation, migration, and invasion and EMT." (PMID 39595579, 2024). "In cancer studies, overexpressed STAT3 has been associated with IL-6–induced MMP9 release, which favors invasiveness/metastasis." (PMID 37982695, 2024). "Studies have shown that a monoclonal antibody targeting PTK7 can diminish cancer cell invasion by decreasing MMP9 secretion." (PMID 39415846, 2024). "MMPs, particularly MMP2 and MMP9, are crucial zinc‐dependent endopeptidases that facilitate cancer cell migration." (PMID 39415846, 2024). "MMP-9 can destroy type IV collagen, which exists in the basement membrane of the extracellular matrix and elevates cancer metastasis." (PMID 39062099, 2024). "These ERKs increase the production and activity of MMP-9 (matrix metalloproteinase-9), an enzyme that breaks down the surrounding tissue matrix, allowing cancer cells to invade nearby tissues." (PMID 39124905, 2024). "MMP-9 plays a role in a wide variety of cancers due to its effects on immune cell infiltration, and it has shown potential to determine prognosis." (PMID 39247608, 2024). "A high level of MMP-2 and MMP-9 has been found in several cancer types, such as those of the bladder, breast, bronchopulmonary, cervical, colon, glioma, larynx, lung, ovary, melanoma, myeloma, esophagus, pancreas, prostate, skin, and stomach." (PMID 38672151, 2024). "This self‐assembly is activated by the enzymatic release of surface‐bound zwitterionic tetrapeptides in the presence of MMP‐9, which is overexpressed in cancer cells." (PMID 39439489, 2024). "Based on this approach, the MMP-9 levels in healthy and malignant cell lines were evaluated, and different cancer cell metastasis capacities were also compared, which has rarely been detected in previous investigations." (PMID 38240894, 2024). "Several research groups have proposed strategies for enhancing MMP inhibitors’ effectiveness, particularly MMP-2 and MMP-9, in cancer treatments." (PMID 39063556, 2024). "CEBPD has been identified as a regulator of MMP1, MMP3, and MMP9 in the gene profiles of cancer cells." (PMID 38419037, 2024). "Multiple studies indicate that EGCG possesses anti-migratory and anti-cancer properties associated with the downregulation of MMP-2 and MMP-9." (PMID 39335164, 2024). "ImmunoArray analysis also indicated a decrease in the protein levels of MMP-9 and VEGF R3, both linked to the formation of blood vessels and cancer metastasis." (PMID 39000524, 2024). "CD151 also induces MMP9 expression and promotes extracellular matrix degradation and cancer cell migration, which contribute to HCC metastasis." (PMID 39085893, 2024).